POLR2K (RNA polymerase II, I and III subunit K)
Description:
DNA-dependent RNA polymerase catalyzes the transcription of DNA into RNA using the four ribonucleoside triphosphates as substrates. Common component of RNA polymerases I, II and III which synthesize ribosomal RNA precursors, mRNA precursors and many functional non-coding RNAs, and a small RNAs, such as 5S rRNA and tRNAs, respectively.
Synonyms: RPB7.0; RPB10alpha; RPB12; ABC10-alpha; RPABC4; hRPB7.0; hsRPB10a
Tractability: Small molecule: a structure with a bound ligand is known. PROTAC: ubiquitination databases record sites on it; its protein half-life has been measured.
Gene: Protein-coding gene on chromosome 8 (100,150,622 to 100,154,005, forward strand). Ensembl gene ENSG00000147669.
Subcellular location: Nucleus; Nucleus, nucleolus
Subcellular location (Human Protein Atlas): Nucleoli fibrillar center
Pathways (Reactome):
Gene expression (Transcription): B-WICH complex positively regulates rRNA expression; Formation of RNA Pol II elongation complex; Formation of the Early Elongation Complex; MicroRNA (miRNA) biogenesis; NoRC negatively regulates rRNA expression; PIWI-interacting RNA (piRNA) biogenesis; RNA Pol II CTD phosphorylation and interaction with CE; RNA Polymerase I Promoter Escape; RNA Polymerase I Transcription Initiation; RNA Polymerase I Transcription Termination; RNA Polymerase II Pre-transcription Events; RNA Polymerase II Promoter Escape; RNA Polymerase II Transcription Elongation; RNA Polymerase II Transcription Initiation; RNA Polymerase II Transcription Initiation And Promoter Clearance; RNA Polymerase II Transcription Pre-Initiation And Promoter Opening; RNA Polymerase III Abortive And Retractive Initiation; RNA Polymerase III Chain Elongation; RNA Polymerase III Transcription Initiation From Type 1 Promoter; RNA Polymerase III Transcription Initiation From Type 2 Promoter; RNA Polymerase III Transcription Initiation From Type 3 Promoter; RNA Polymerase III Transcription Termination; RNA polymerase II transcribes snRNA genes; Transcriptional regulation by small RNAs
Disease: Abortive elongation of HIV-1 transcript in the absence of Tat; Dengue Virus-Host Interactions; Formation of HIV elongation complex in the absence of HIV Tat; Formation of HIV-1 elongation complex containing HIV-1 Tat; Formation of the HIV-1 Early Elongation Complex; HIV Transcription Initiation; HIV elongation arrest and recovery; Pausing and recovery of HIV elongation; Pausing and recovery of Tat-mediated HIV elongation; RNA Pol II CTD phosphorylation and interaction with CE during HIV infection; RNA Polymerase II HIV Promoter Escape; Signaling by FGFR2 IIIa TM; Tat-mediated HIV elongation arrest and recovery; Tat-mediated elongation of the HIV-1 transcript; Transcription of the HIV genome
and 15 more pathways
Gene Ontology:
Molecular function: protein binding; DNA-directed RNA polymerase activity; zinc ion binding; DNA binding
Biological process: termination of RNA polymerase III transcription; transcription by RNA polymerase II; transcription by RNA polymerase III; transcription elongation by RNA polymerase I; transcription elongation by RNA polymerase II; transcription initiation at RNA polymerase II promoter; transcription initiation at RNA polymerase III promoter; nucleolar large rRNA transcription by RNA polymerase I; regulation of transcription by RNA polymerase I; termination of RNA polymerase I transcription; transcription initiation at RNA polymerase I promoter; DNA-templated transcription
Cellular component: fibrillar center; nucleus; RNA polymerase I complex; RNA polymerase II, core complex; RNA polymerase III complex; cytosol; nucleoplasm; nucleolus
Homologues: Orthologues: chimpanzee POLR2K (100% identical), pig POLR2K (100% identical), rat Polr2k (100% identical), mouse Polr2k (98% identical), guinea pig POLR2K (97% identical), zebrafish polr2k (95% identical), tropical clawed frog polr2k (91% identical), Drosophila melanogaster Polr2K (67% identical), Caenorhabditis elegans rpb-12 (64% identical).
Diseases named in the same sentence as POLR2K in open-access papers:
POLR2K is named in the same sentence as 7 diseases in open-access papers, as found by Europe PMC text mining. Sharing a sentence is not in itself a finding about the gene and the disease. The quoted sentences say what the papers report.
breast carcinoma (4 papers, 2021 to 2023). "The expression of DGAT1, DUT, LYPLA1, and POLR2K was linked to an increased risk of breast cancer, whereas SMPD4 was associated with a protective effect." (PMID 37644433, 2023). "LYPLA1 was found to be associated with poor prognosis in lung adenocarcinoma, while POLR2K was identified as one of the top 10 cancer immunotherapy proteins related to breast cancer by machine-learning predictions." (PMID 37644433, 2023). "In our study, the PARP3, POLR2K, PSMB1, and PSMD2 genes were significantly associated with the overall survival of patients with breast cancer, and the high expression levels of POLR2K, PSMB1, and PSMD2 were related to low survival rates." (PMID 37350936, 2023). "Moreover, among these components, POLR2K seems to be markedly altered amongst all breast cancer subtypes, with 11% of cases exhibiting amplification." (PMID 34071360, 2021). "Moreover, three DDR genes, POLR2K, PSMB1, and PSMD2, which are closely linked to tumorigenesis, may be used as potential biomarkers for predicting the prognosis of patients with breast cancer." (PMID 37350936, 2023).
colorectal cancer (1 paper, 2014). A primary or metastatic malignant neoplasm that affects the colon or rectum. "The first miRNA, already associated with colorectal cancer, regulates polymerase (RNA) II polypeptide K (POLR2K), which is involved in the transcription of DNA into RNA." (PMID 24866763, 2014).
pneumonia (1 paper, 2023). An acute, acute and chronic, or chronic inflammation focally or diffusely affecting the lung parenchyma, caused by an infection in one or both of the lungs (by bacteria, viruses, fungi, or mycoplasma.). "In a previous study investigating the pathogenesis of pneumonia, POLR2K was found to encode crucial proteins in the PPI network." (PMID 37035734, 2023).
cancer (5 papers, 2019 to 2025). A tumor composed of atypical neoplastic, often pleomorphic cells that invade other tissues. "Similarly, upregulation of SLC2A6 (A.K.A. GLUT6) was reported to promote glucose uptake 39, while POLR2K upregulation was found to increase nucleic acid metabolism 40 in aggressive cancers." (PMID 30945298, 2019). "Best predicted cancer immunotherapy proteins with BC were RPS27, SUPT4H1, CLPSL2, POLR2K and RPL38, and the most altered ones were POLR2K, ASH2L, MED30, NSL1 and RPRD2." (PMID 32444848, 2020). "Upregulation of POLR2K may facilitate Pol III assembly, which is required for protein synthesis, contributing to cell proliferation and cancer development." (PMID 37035734, 2023). "Upregulation of POLR2K may facilitate Pol III assembly, contributing to cell proliferation and cancer development." (PMID 37035734, 2023).
POLR2K also shares sentences with these, for which no sentence is quoted: tumor (2 papers); lung adenocarcinoma (1); primary ciliary dyskinesia (1).